AQP12B (aquaporin 12B)
Description:
Putative aquaporin. Could form homotetrameric transmembrane channels, with each monomer independently mediating water transport across the plasma membrane along its osmotic gradient.
Synonyms: INSSA3
Tractability: Antibody: UniProt predicts a signal peptide or a membrane-spanning region.
Gene: Protein-coding gene on chromosome 2 (240,676,418 to 240,682,906, reverse strand). Ensembl gene ENSG00000185176.
Subcellular location: Membrane
Gene Ontology:
Molecular function: water channel activity; channel activity
Biological process: intracellular water homeostasis; transmembrane transport; water transport
Cellular component: plasma membrane; membrane
Genetic constraint (gnomAD): Loss-of-function variants: 8 observed, 6.43 expected, observed/expected ratio (o/e) 1.24, 90% interval 0.71 to 1.88. That is too few expected variants to judge how well the gene tolerates losing a copy. Missense variants: 236 observed, 207.15 expected, observed/expected ratio (o/e) 1.14, 90% interval 1.02 to 1.27. Synonymous variants: 116 observed, 110.01 expected, observed/expected ratio (o/e) 1.05, 90% interval 0.91 to 1.23.
Homologues: Orthologues: chimpanzee AQP12B (97% identical), macaque AQP12 (91% identical), mouse Aqp12 (70% identical), rat Aqp12a (70% identical), dog AQP12 (68% identical), zebrafish aqp12 (37% identical), Drosophila melanogaster AQP (22% identical), Caenorhabditis elegans aqp-10 (20% identical), Caenorhabditis elegans aqp-9 (19% identical), Caenorhabditis elegans aqp-11 (17% identical). Paralogues in human: AQP12A (95% identical), AQP11 (25% identical).
Diseases named in the same sentence as AQP12B in open-access papers:
AQP12B is named in the same sentence as 2 diseases in open-access papers, as found by Europe PMC text mining. Sharing a sentence is not in itself a finding about the gene and the disease. The quoted sentences say what the papers report.
cancer (1 paper, 2021). A tumor composed of atypical neoplastic, often pleomorphic cells that invade other tissues. "Other DVPs for solid cancers were annotated to genes related to bladder (TBC1D12), breast (AQP12B) or lung, prostate and colorectal (GFI1) cancers." (PMID 33632303, 2021).
AQP12B also shares sentences with these, for which no sentence is quoted: tumor (1 paper).